GAR1 (GAR1 ribonucleoprotein)
Description:
Required for ribosome biogenesis and telomere maintenance. Part of the H/ACA small nucleolar ribonucleoprotein (H/ACA snoRNP) complex, which catalyzes pseudouridylation of rRNA. This involves the isomerization of uridine such that the ribose is subsequently attached to C5, instead of the normal N1. Each rRNA can contain up to 100 pseudouridine ('psi') residues, which may serve to stabilize the conformation of rRNAs. May also be required for correct processing or intranuclear trafficking of TERC, the RNA component of the telomerase reverse transcriptase (TERT) holoenzyme.
Synonyms: NOLA1
Tractability: PROTAC: UniProt records ubiquitination sites on it; ubiquitination databases record sites on it; its protein half-life has been measured.
Gene: Protein-coding gene on chromosome 4 (109,815,500 to 109,825,575, forward strand). Ensembl gene ENSG00000109534.
Subcellular location: Nucleus, nucleolus; Nucleus, Cajal body
Subcellular location (Human Protein Atlas): Nucleoli fibrillar center; Nucleoplasm
Pathways (Reactome):
Cell Cycle: Telomere Extension By Telomerase
Metabolism of RNA: rRNA modification in the nucleus and cytosol
Gene Ontology:
Molecular function: box H/ACA snoRNA binding; protein binding; RNA binding; telomerase RNA binding
Biological process: telomere maintenance via telomerase; snoRNA guided rRNA pseudouridine synthesis; pseudouridine synthesis; ribosome biogenesis
Cellular component: box H/ACA snoRNP complex; box H/ACA telomerase RNP complex; chromosome, telomeric region; fibrillar center; telomerase holoenzyme complex; box H/ACA scaRNP complex; nucleoplasm; Cajal body; nucleolus
Genetic constraint (gnomAD): Loss-of-function variants: 4 observed, 8.04 expected, observed/expected ratio (o/e) 0.5, 90% interval 0.24 to 1.14. That is too few expected variants to judge how well the gene tolerates losing a copy. Missense variants: 99 observed, 102.34 expected, observed/expected ratio (o/e) 0.97, 90% interval 0.82 to 1.14. Synonymous variants: 31 observed, 39.01 expected, observed/expected ratio (o/e) 0.79, 90% interval 0.6 to 1.07.
Homologues: Orthologues: chimpanzee GAR1 (99% identical), macaque GAR1 (99% identical), mouse Gar1 (96% identical), rabbit GAR1 (94% identical), pig GAR1 (93% identical), guinea pig GAR1 (92% identical), zebrafish gar1 (82% identical), rat Gar1 (80% identical), tropical clawed frog gar1 (76% identical), Drosophila melanogaster Gar1 (65% identical), Caenorhabditis elegans garr-1 (64% identical).
Diseases named in the same sentence as GAR1 in open-access papers:
GAR1 is named in the same sentence as 17 diseases in open-access papers, as found by Europe PMC text mining. Sharing a sentence is not in itself a finding about the gene and the disease. The quoted sentences say what the papers report.
chronic lymphocytic leukaemia (1 paper, 2019). "As GAR1-deficiencies are implicated in chronic lymphocytic leukaemia and contribute to telomere dysfunction, we suggest that this cancer may be acutely sensitive to G4-stabilisation by small molecules." (PMID 31287417, 2019).
heart failure (1 paper, 2025). Inability of the heart to pump blood at an adequate rate to meet tissue metabolic requirements. "The use of the preferable GaR1 antagonist M40 resulted in enhanced cardiac function and reduced remodeling in rats with heart failure." (PMID 39968178, 2025).
lung adenocarcinoma (1 paper, 2023). A carcinoma that arises from the lung and is characterized by the presence of malignant glandular epithelial cells. "Furthermore, low expression levels of the other RNP core protein components NHP2, NOP10, and GAR1 were also associated with poor prognosis levels in lung SCC and ovarian cancer, but not in lung adenocarcinoma or HNSCC." (PMID 36732018, 2023).
lung carcinoma (1 paper, 2021). "DKC1 and GAR1 were also expressed at high levels in lung cancer samples." (PMID 33288886, 2021).
cancer (2 papers, 2019 to 2023). A tumor composed of atypical neoplastic, often pleomorphic cells that invade other tissues. "Finally, we determined the effect of 10 individual factors on OS and observed that higher expression of DKC1, NVL, and GAR1 were significantly associated with nine, three, and three cancer types, respectively." (PMID 36239411, 2023).
GAR1 also shares sentences with these, for which no sentence is quoted: anemia (1 paper); autism (1); Depression (1); ischaemic stroke (1); monoclonal gammopathy of undetermined significance (1); myeloma (1); neuroblastoma (1); ovarian carcinoma (1); plasma cell disorders (1); plasma cell leukemia (1); tumor (1); Wilson disease (1).